MIR16-1 (microRNA 16-1)
Synonyms: hsa-mir-16-1; MIRN16-1; miRNA16-1; mir-16-1
Gene: MicroRNA gene on chromosome 13 (50,048,973 to 50,049,061, reverse strand). Ensembl gene ENSG00000208006.
Gene Ontology:
Biological process: miRNA-mediated post-transcriptional gene silencing
Cellular component: RISC complex
Diseases named in the same sentence as MIR16-1 in open-access papers:
MIR16-1 is named in the same sentence as 5 diseases in open-access papers, as found by Europe PMC text mining. Sharing a sentence is not in itself a finding about the gene and the disease. The quoted sentences say what the papers report.
B-cell chronic lymphocytic leukemia (2 papers, 2020 to 2025). "These genes may include MIR142, for which somatic mutations have been identified in various blood cancers, or MIR15A and MIR16-1, which are commonly deleted and/or mutated in chronic lymphocytic leukemia." (PMID 40867048, 2025).
prostate carcinoma (1 paper, 2024). A carcinoma that arises from epithelial cells of the prostate gland. "In addition to CLL, decreased expression of MIR16-1, as well as MIR15A, has been observed in multiple cancers, including breast, lung, colon, ovarian, and prostate cancer." (PMID 38261968, 2024).
tumor (1 paper, 2022). "Bioinformatics analysis using KEGG pathways enrichment, shows that Menin plays a tumor suppressor role in normal prostate model PNT1A probably through microRNAs regulation (e.g., MIR1-2; MIR16-1; let-7d) known for their tumor suppressor roles in PC." (PMID 34711954, 2022).
MIR16-1 also shares sentences with these, for which no sentence is quoted: blood cancers (1 paper); cancer (1).